PIK3CA (phosphatidylinositol-4,5-bisphosphate 3-kinase catalytic subunit alpha)
Diseases named in the same sentence as PIK3CA in open-access papers (continued):
Sharing a sentence is not in itself a finding about the gene and the disease.
esophageal squamous cell carcinoma (29 papers, 2012 to 2026). Esophageal squamous cell carcinoma (ESCC) is a type of esophageal carcinoma (EC) that can affect any part of the esophagus, but is usually located in the upper or middle third. "Several seminal studies, using either whole-genome sequencing or whole-exome sequencing with large sample sizes, have repeatedly confirmed the heavy implications of hotspot PIK3CA mutations in esophageal squamous cell carcinoma (ESCC) clinical tissues." (PMID 38616230, 2024). "PIK3CA mutation is associated with a better disease-free survival and overall survival in esophageal squamous cell carcinoma." (PMID 36119057, 2022). "The PI3K-AKT signaling is a complex pathway that regulates cell growth, proliferation, motility, apoptosis, and cell growth and is often related to the development of esophageal squamous cell carcinoma through driver mutations in the PIK3CA gene." (PMID 34663841, 2021). "Silencing or inhibition of LOX has been reported to suppress the migration, invasion, and growth ability of esophageal squamous cell carcinoma by downregulating PIK3 harboring a PIK3CA mutation." (PMID 34202354, 2021). "Recently, PIK3CA mutations were identified in 21.7% of chagasic megaesophagus associated with esophageal squamous cell carcinoma cases." (PMID 31905960, 2019). "The detection of PIK3CA mutations in benign chagasic megaesophagus lesions suggests their putative role in esophageal squamous cell carcinoma development and opens new opportunities for targeted-therapies for these diseases." (PMID 30619505, 2018). "PIK3CA mutations are expected to be potential therapeutic targets for esophageal squamous cell carcinoma (ESCC)." (PMID 28068934, 2017). "Using FFPEs, we successfully screened 80 metastatic esophageal SCC and have identified PIK3CA mutation (11.5%) and BRAF mutation (1.2%) as potential targets for further therapeutic development." (PMID 22870241, 2012). "Of 11 mutations, 4 mutations were located in PIK3CA, thus the most frequently observed somatic mutations in esophageal SCC." (PMID 22870241, 2012). "There is one study which directly sequenced tumor DNA isolated from FFPE and identified 4 of 35 (11.8%) esophageal SCC to have PIK3CA mutation." (PMID 22870241, 2012). "We identified that 11% of metastatic esophageal SCC had PIK3CA mutations in exon 9 (E542K, E545K) and exon 20 (H1047R, L) and that 1% of the patients harbored BRAF V600E mutations." (PMID 22870241, 2012). "There are scarce reports on PIK3CA mutations in esophageal SCC." (PMID 22870241, 2012). "In conclusion, this is the first study that analyzed and identified PIK3CA activating mutations in patients with esophageal squamous cell carcinomas associated with chagasic megaesophagus (CM/ESCC), which were associated with a worse outcome." (PMID 30619505, 2018). "Similarly, Shigaki and colleagues found in a series of 219 patients who had undergone curative resection of stage I–III esophageal squamous cell carcinoma that patients with PIK3CA mutations experienced significantly longer DFS, CSS, and OS than those with wild-type PIK3CA49." (PMID 25641861, 2015). "We analyzed hotspot PIK3CA gene mutations in a series of esophageal squamous cell carcinomas associated or not with chagasic megaesophagus, as well as, in chagasic megaesophagus biopsies." (PMID 30619505, 2018).
esophageal squamous cell carcinoma (continued). "LINC01518 is overexpressed in oesophageal squamous cell carcinoma (ESCC) tissues, and it sponges miR-1-3p to promote the PIK3CA/Akt pathway to promote cell proliferation and inhibit apoptosis in ESCC cells." (PMID 40594481, 2025). "Gain-of-function PIK3CA mutations, such as PIK3CAH1047R, are recurrently found in tumors, including esophageal squamous cell carcinoma (ESCC), benign overgrowth syndromes and vascular malformations." (PMID 39169259, 2024). "While PIK3CA amplifications have previously been reported in HPV+ HNSCC, SOX2 has recently been proposed as the critical target of 3q gains observed at a high frequency in squamous lung cancer and in esophageal squamous cell carcinoma." (PMID 23718828, 2013).
gynecologic cancers (29 papers, 2014 to 2025). "Slide-mounted FFPE tumor samples were obtained from patients with activating PIK3CA mutations in their ER+ or HER+ breast or gynecological cancers, respectively, prior to treatment in a multicenter phase I clinical trial of capivasertib (NCT01226316)." (PMID 38954770, 2024). "PIK3CA amplification and mutations are common in gynecological cancers, yet their role as biomarkers remains debated." (PMID 38920692, 2024). "Multi‐PIK3CA mutations were present in 10.3% of all PIK3CA‐mutant tumors, predominantly occurring in breast and gynecological cancers." (PMID 39054873, 2024). "Digestive tract cancers and gynecological cancers were equally represented with 27 patients (20.8%) each and 27 PIK3CA mutations (20%)." (PMID 36934165, 2023). "The 3 main tumor locations associated with PIK3CA mutations were breast, digestive tract and gynecological cancers." (PMID 36934165, 2023). "Recently, one published clinical study shows that patients with PIK3CA-mutated breast or gynecologic cancer were given the capivasertib from 480 to 800 mg in the clinic." (PMID 31805962, 2019). "Moreover, several case reports and clinical studies indicate that alpelisib is well tolerated and demonstrates activity in patients with advanced gynecologic cancers harboring activating mutations in PIK3CA (NCT01219699, NCT04085653)." (PMID 41315187, 2025). "This mutation is one of the most common PIK3CA mutations in gynecologic cancers." (PMID 39394200, 2024). "In two cases of gynecological cancer harboring the same mutation in PIK3CA and PTEN, the drug response profiles were completely distinct, showing that, used together, PDTO and NGS/WES could better select patients who could benefit from these therapies." (PMID 36010869, 2022). "In PIK3CA, we identified p.T957 co-clustering with the highly recurrent p.H1047R that affects many gynecologic cancer cases, including 13.8% of breast invasive carcinoma (BRCA), 7% of uterine carcinosarcoma (UCS), and 5.8% of uterine corpus endometrial carcinoma (UCEC)." (PMID 33875650, 2021). "Previous reports suggested that PIK3CA mutations might predict sensitivity to treatment with PI3K/AKT/mTOR inhibitors, such as everolimus, in multiple tumor types including gynecologic cancer." (PMID 33207545, 2020). "Similar results were also reported for AZD5363, although exclusive PIK3CA mutations did not correlate with increased response in another study in breast or gynecological cancer patients where concurrent mutations in KRAS, NRAS, HRAS, or BRAF were excluded." (PMID 31835495, 2019). "In gynecological cancers, it has also been reported that gene alterations of PTEN and PIK3CA are more frequent." (PMID 34683075, 2021). "ERBB2, PIK3CA, ARID1A, and KRAS would be key molecular targets in gynecological cancers." (PMID 38201563, 2023).
rectal cancer (29 papers, 2012 to 2025). A primary or metastatic malignant neoplasm that affects the rectum. "Our study provides evidence for the benefits of concurrent aspirin use with neoadjuvant CRT for rectal cancer, which appears to be independent from tumor PIK3CA mutation status, suggesting a broader indication for aspirin in this clinical setting." (PMID 33430037, 2021). "Taking into account the potential heterogeneity of tumor behavior between colon and rectal carcinomas, anti-cancer effects of aspirin according to PIK3CA mutation status in rectal cancer cells and human primary cells should be examined in future studies." (PMID 29152088, 2017). "A recent study determined the prognostic value of PIK3CA mutations in 240 non- irradiated resectable stages I to III rectal cancer patients from the Dutch TME trial." (PMID 23617638, 2013). "PIK3CA mutations occurred more frequently in colon than in rectal cancers (P = 0.014)." (PMID 29666387, 2018). "In this study, we aimed to determine the mutation frequencies of KRAS, BRAF and PIK3CA and to establish whether such mutations may be used as prognostic and/or predictive factors in rectal cancer patients." (PMID 23617638, 2013). "Interestingly, both BRAF (P=0.000) and PIK3CA (P=0.011) mutations were significantly more frequent in colon than in sigmoid or rectal carcinomas." (PMID 23548132, 2013). "The five most frequently altered potentially targetable genes in colon and rectal cancer were PIK3CA (19.6% and 14.2%), PTEN (8.7% and 5.9%), ERBB2 (4.7% and 6.0%), EGFR (2.5% and 2.0%), and FGFR1 (2.0% and 2.7%)." (PMID 39865537, 2025). "Frequencies of tumor KRAS, BRAF, and PIK3CA point mutations and ERBB2 amplification in 63 patients with locally advanced rectal cancer." (PMID 23226389, 2012). "Point mutations in KRAS, BRAF, and PIK3CA and ERBB2 amplification were determined in primary tumors from 63 patients with locally advanced rectal cancer scheduled for radical treatment." (PMID 23226389, 2012). "A similar pattern was detectable in rectal cancer, where PIK3CA and PTEN alterations were significantly overrepresented in the RAS/BRAF‐altered subgroup and EGFR, ERBB2, FGFR1, and FGFR3 alterations were significantly overrepresented in the RAS/BRAF‐wt subgroup." (PMID 39865537, 2025). "Research has shown that PIK3CA may control the JAK-STAT downstream pathway to influence the development of rectal cancer and renal cell carcinoma." (PMID 38784043, 2024). "Based on RNA-seq data from a subset of our rectal cancer patient population, neither PIK3CA or KRAS mutational status, nor COX-2 mRNA expression were associated with the benefit of aspirin use or tumor downstaging." (PMID 33430037, 2021). "The lower frequency of PIK3CA mutations in rectal cancer may, in part, explain the lack of association between type 2 diabetes and rectal cancer." (PMID 39131121, 2022). "Other genes that have been studied in rectal cancer with contrasting results include BRAF, PIK3CA, SMAD4, and tumor MSI." (PMID 36900260, 2023). "Mutations in both the MAPK/ERK pathway (e.g. BRAF, KRAS, NRAS, ERBB2, and ERBB3) and the PI3K/AKT/mTOR pathway (e.g. PIK3CA, IGF2, PTEN, and PIK3R1) are frequent in rectal cancer." (PMID 34321074, 2021). "Therefore, in this study, we characterized the clinical and molecular features of HER2 amplification in CRC and investigated the differential incidence of RAS/RAF and PIK3CA alterations in patients with HER2-amplified colon and rectal cancer." (PMID 40742050, 2025).
invasive breast carcinoma (27 papers, 2014 to 2026). A carcinoma that infiltrates the breast parenchyma. "This study analyzed 283 Chinese women with invasive breast cancer and found a PIK3CA mutation rate of 41%, with exon 20 mutations being the most common (62.1%)." (PMID 40472482, 2025). "A total of 116 PIK3CA mutations were detected in 283 invasive breast cancer tissue samples, representing a mutation rate of 41%." (PMID 40472482, 2025). "Retrospective analysis of the medical records of 220 consecutive patients with invasive breast cancer was reviewed according to the PIK3CA-mutated molecular tumor subtype." (PMID 38025526, 2023). "Accordingly, the NCCN Guidelines for invasive breast cancer (version 1.2022) recommend assessment for PIK3CA mutations using tumor tissue or ctDNA testing, with reflex tumor testing if the ctDNA results are negative." (PMID 37958763, 2023). "Analysed by the Molecular Tumor Board Portal, PIK3CA bears somatic protein-affecting mutations in 35.4% of the invasive breast carcinoma samples (n=1297) and 14.0% of the pan-cancer samples (n=10703)." (PMID 36046364, 2022). "In breast invasive carcinoma, this subtype shows a low mutation load (fewer number of somatic missense mutations and frameshift deletion) and is enriched with mutations in PIK3CA, with moderate immune activities and slow tumor growth." (PMID 32391377, 2020). "While currently indicated for testing in breast invasive carcinoma only, PIK3CA mutations were present across multiple tumor types, suggesting that clinical trials with PIK3CA inhibitors could be considered in the future, if clinically appropriate." (PMID 38200255, 2024). "The occurrence of PIK3CA mutations was explored both in in situ and in invasive breast cancers and the conclusion was reached that its frequency is similar in these two tumors, thus supporting the concept that it is more likely to play a role in breast tumor initiation than in invasive progression." (PMID 32210163, 2020). "Furthermore, we discovered that different types of genetic abnormalities (mutation versus amplification) within the same cancer driver gene (PIK3CA or GATA3) were associated with opposite histologic changes in invasive breast cancer." (PMID 27283966, 2016). "The first patient is a 69-year-old woman with left breast invasive carcinoma (ER+, PR+, HER2-), status post bilateral mastectomy, adjuvant chest and axillary radiation, and aromatase inhibitor therapy, with two PIK3CA gain of function mutations." (PMID 40122972, 2025). "Remarkably, we discovered that different subtypes of genetic aberrations within a single cancer driver gene, such as PIK3CA or GATA3, are associated with opposite histologic changes in invasive breast cancer." (PMID 27283966, 2016). "Two driver genes dominate across all subtypes of invasive breast cancer: PIK3CA and TP535." (PMID 35768433, 2022). "Here we provide evidence that JP shows recurrent PIK3CA mutations, and that it may constitute the substrate from which DCIS and invasive breast cancers develop, given that we documented clonal relatedness between JP and associated carcinoma." (PMID 33263939, 2021). "The frequency of PIK3CA mutation and amplification was various and their clinical significances have not been clarified in Korean patients with invasive breast carcinoma (IBC)." (PMID 32410843, 2020). "For example, PIK3CA and GATA3 genes may carry a mutation or amplification in invasive breast cancer." (PMID 27283966, 2016).